MIA-RAB4B (MIA-RAB4B readthrough (NMD candidate))
Gene: Protein-coding gene on chromosome 19 (40,771,648 to 40,796,943, forward strand). Ensembl gene ENSG00000268975.
Genetic constraint (gnomAD): Missense variants: 158 observed, 179.63 expected, observed/expected ratio (o/e) 0.88, 90% interval 0.77 to 1. Synonymous variants: 57 observed, 69.44 expected, observed/expected ratio (o/e) 0.82, 90% interval 0.66 to 1.02.